CRABP2 (cellular retinoic acid binding protein 2)
Description:
Transports retinoic acid to the nucleus. Regulates the access of retinoic acid to the nuclear retinoic acid receptors.
Synonyms: CRABP-II; RBP6
Tractability: Small molecule: a structure with a bound ligand is known; it has a high-quality binding pocket. PROTAC: it is named in the literature on targeted protein degradation; UniProt records ubiquitination sites on it; ubiquitination databases record sites on it; a small molecule that binds it is known.
Target class: Fatty acid binding protein family; Auxiliary transport protein
Gene: Protein-coding gene on chromosome 1 (156,699,597 to 156,708,094, reverse strand). Ensembl gene ENSG00000143320.
Subcellular location: Cytoplasm; Endoplasmic reticulum; Nucleus
Subcellular location (Human Protein Atlas): Cytosol; Nucleoplasm
Pathways (Reactome):
Signal Transduction: Signaling by Retinoic Acid
Gene Ontology:
Molecular function: cyclin binding; protein binding; fatty acid binding; retinoic acid binding; retinoid binding; lipid binding
Biological process: epidermis development; fatty acid transport; regulation of DNA-templated transcription; signal transduction
Cellular component: cytoplasm; cytosol; extracellular exosome; nucleoplasm; nucleus; endoplasmic reticulum
Genetic constraint (gnomAD): Loss-of-function variants: 20 observed, 19.14 expected, observed/expected ratio (o/e) 1.04, 90% interval 0.73 to 1.52. The upper end of that interval is the gene's LOEUF score, 1.52, which puts it in group 6 of 6, group 1 being the genes least tolerant of losing a copy. Missense variants: 151 observed, 177.85 expected, observed/expected ratio (o/e) 0.85, 90% interval 0.74 to 0.97. Synonymous variants: 76 observed, 70.39 expected, observed/expected ratio (o/e) 1.08, 90% interval 0.9 to 1.31.
Homologues: Orthologues: chimpanzee CRABP2 (100% identical), macaque CRABP2 (99% identical), guinea pig CRABP2 (97% identical), pig CRABP2 (96% identical), mouse Crabp2 (93% identical), rabbit CRABP2 (90% identical), rat Crabp2 (85% identical), tropical clawed frog crabp2 (76% identical), zebrafish crabp2a (75% identical), zebrafish crabp2b (70% identical), dog CRABP2 (68% identical), Caenorhabditis elegans lbp-7 (32% identical), and 2 more. Paralogues in human: CRABP1 (75% identical), FABP3 (39% identical), FABP7 (38% identical), RBP1 (35% identical), FABP12 (33% identical), FABP9 (33% identical), PMP2 (33% identical), FABP4 (33% identical), RBP7 (33% identical), FABP2 (29% identical), FABP5 (28% identical), RBP2 (28% identical), and 3 more.
Diseases named in the same sentence as CRABP2 in open-access papers:
CRABP2 is named in the same sentence as 98 diseases in open-access papers, as found by Europe PMC text mining. Sharing a sentence is not in itself a finding about the gene and the disease. The quoted sentences say what the papers report.
breast carcinoma (34 papers, 2014 to 2025). "Up-regulated transcripts and proteins included LGALS2, which has been implicated to restrain tumor progression in colorectal and breast cancer, as well as CRABP2, whose overexpression has been associated with decreased invasiveness of ER+ breast cancer cells." (PMID 40073121, 2025). "Survival analysis was carried out using Kaplan-Meier and found that the high mRNA levels of CRABP2 were markedly associated with higher and lower patient survival probability in ER+ and ER− breast cancer respectively." (PMID 31419991, 2019). "One report stated that messenger ribonucleic (mRNA) expression of CRABP2 in breast cancer is associated to the status of ER, progesterone receptor (PR), and human epidermal growth factor receptor 2 (Her2)." (PMID 31419991, 2019). "Next, from the clinicopathologic status of mammary cancer, we investigated the expression levels of CRABP2 and their association with the patients." (PMID 31419991, 2019). "Consistently, low levels of PDCD4 in breast tumors have been associated with poor prognosis and high CRABP2 levels have been shown to be indicative of longer overall survival in breast cancer patients." (PMID 24870930, 2014). "Furthermore, CRABP2 overexpression has been linked to chemotherapy resistance in both ovarian and breast cancers." (PMID 40371351, 2025). "The expression of CRABP2 in breast cancer tissues is significantly up-regulated, and it may become a new diagnostic marker for breast cancer." (PMID 38195606, 2024). "We found that deficient CRABP2 promoted ER+ breast cancer cells migration and invasion." (PMID 31419991, 2019). "For example, CRABP2 inhibits the invasion and metastasis of ER + breast cancer and facilitates the metastasis of ER- breast cancer by regulating the stability of Lats1." (PMID 38807101, 2024). "CRABP2 is highly expressed in docetaxel-resistant breast carcinoma and promotes invasion and metastasis in ER-negative breast cancer." (PMID 39768218, 2024). "A single study suggested CRABP2 to acts as a tumor inhibitor in esophageal carcinoma, while in breast cancer, CRABP2 can both suppress or promote tumor invasion depending on tumor type." (PMID 37688629, 2023). "In ER + breast cancer cells, CRABP2 suppresses tumor metastasis by inhibiting ubiquitination of Lats1; while CRABP2 enhances ubiquitination of Lats1 and promotes tumor metastasis." (PMID 36568517, 2022). "The expression of CRABP2 was significantly higher in breast cancer than normal controls in subgroup analysis based on gender, age, menopause status, disease stage, nodal metastasis status, and molecular subtypes (all P < 0.05)." (PMID 33407865, 2021). "Previous studies have identified the biological function of CRABP2 in the metastasis of breast cancer and lung cancer." (PMID 33879199, 2021). "In breast cancer, lung cancer, liver cancer, and Wilms tumor, CRABP2 plays a role in promoting cancer." (PMID 34632074, 2021). "What’s more, although the MDA-MB-468 cells were ER− breast cancer cells, CRABP2 was highly expressed in MDA-MB-468 cells." (PMID 31419991, 2019). "In general, our study has identified the role of CRABP2 in breast cancer invasion and metastasis, which further depends on Hippo-Lats1 and ER status." (PMID 31419991, 2019). "Then we checked the effects of CRABP2 overexpression on TEAD luciferase activity in ER− breast cancer cells." (PMID 31419991, 2019). "Immunohistochemical staining method was used to analyze the expression of CRABP2 in human breast cancer tissues." (PMID 31419991, 2019). "However, how CRABP2 is associated with invasion and metastasis in breast cancer remain unclear." (PMID 31419991, 2019). "One study stated that a high level of CRABP2 mRNA relates to a better prognosis of patients with breast cancer." (PMID 31419991, 2019). "This confirmed that knockdown of ER in ER+ breast cancer cells can reverse CRABP2 inhibition to the EMT of breast cancer cells." (PMID 31419991, 2019).
breast carcinoma (continued). "HuR has been reported in breast cancer to be regulated by Crabp229,30, and here we also found that Crabp2 regulated HuR in lung cancer cells." (PMID 30696915, 2019). "This confirms the contradiction of the correlation between CRABP2 and breast cancer patient prognosis in different studies." (PMID 31419991, 2019). "CRABP2 showed extremely faint staining in ER− breast cancer and in the matched surrounding tissues, but CRABP2 expression was higher in cancer tissues than in the matched surrounding tissues of ER− breast cancer." (PMID 31419991, 2019). "Then we checked the effects of CRABP2 depletion on TEAD luciferase activity in ER+ breast cancer cells." (PMID 31419991, 2019). "Previous studied reports that ER regulated the expression of CRABP2 and CRABP2 had opposite correlation with prognosis of patients with breast cancer." (PMID 31419991, 2019). "Our results show that CRABP2 controls metastasis and invasion of breast cancer through the Hippo pathway." (PMID 31419991, 2019). "The results showed that overexpression of CRABP2 increased the expression of Lats1 when ER was knocked down in ER+ breast cancer cells." (PMID 31419991, 2019). "In this study, we wanted to find the relationship between CRABP2, ER and the invasion and metastasis of breast cancer." (PMID 31419991, 2019). "The results showed that CRABP2 expression was higher in cancer tissues than in the matched surrounding tissues of ER+ breast cancer." (PMID 31419991, 2019). "We continued our studies to further study the relevance of CRABP2 overexpression in ER− mammary cancer by firmly overexpressing CRABP2 in ER− breast cancer cells." (PMID 31419991, 2019). "Conversely, another report indicates that high level of CRABP2 leads to the poor prognosis of patients with breast cancer." (PMID 31419991, 2019). "To better understand the relationship between CRABP2 and prognosis of patients with breast cancer, we analyzed it in ER+ and ER− breast cancer respectively by Kaplan-Meier analysis." (PMID 31419991, 2019). "Our findings indicate that CRABP2 can suppress invasion and metastasis of ER+ breast cancer and promote invasion and metastasis of ER− breast cancer by regulating the stability of Lats1 in vitro and in vivo, and it provides new ideas for breast cancer therapy." (PMID 31419991, 2019). "Previous studies from the database have reported the patients with high expression of CRABP2 showed different prognosis in ER+ and ER− breast cancer." (PMID 31419991, 2019). "Comparing these data leads to confusion and identifying the function of CRABP2 in breast cancer becomes difficult." (PMID 31419991, 2019). "This aim of this study was to explore how CRABP2 regulated invasion and metastasis based on the estrogen receptor-α (herein called ER) status in breast cancer." (PMID 31419991, 2019). "From the previous study, it is known that knockdown of CRABP2 in ER+ mammary cancer cells and overexpression of CRABP2 in ER− mammary cancer cells promote the degradation of Lats1." (PMID 31419991, 2019). "But, overexpression of CRABP2 in ER− mammary cancer cells reduced the protein levels of p-Lats1T1079, Lats1, p-YAPS127 and retained the protein expression of YAP and Mst2." (PMID 31419991, 2019). "In ER+ mammary cancer cells, the interaction of CRABP2 and Lats1 suppresses the ubiquitination of Lats1 to activate Hippo pathway to inhibit the invasion and metastasis of ER+ mammary cancer." (PMID 31419991, 2019). "Now, we know that ER drives the transcription of RARα and subsequently RARα drives the transcription of CRABP2 in ER+ mammary cancer cells." (PMID 31419991, 2019). "d-f The regulation of CRABP2 on metastasis, and invasion depends on Lats1 in ER+ mammary cancer cells." (PMID 31419991, 2019). "At the same time, the high CRABP2 expression level in ER− mammary cancer tissues related to a reduction in patient RFS by Kaplan–Meier analysis." (PMID 31419991, 2019).
breast carcinoma (continued). "The interaction of endogenous and exogenous CRABP2 with Lats1 can regulate Lats1 by regulating ubiquitination of Lats1 in ER+ and ER− mammary cancer cells respectively." (PMID 31419991, 2019). "Our results showed that the low CRABP2 expression level in ER+ mammary cancer tissues significantly related to a reduction in patient relapse-free survival (RFS)." (PMID 31419991, 2019). "Then, we simultaneously overexpressed ER and knocked down CRABP2 in ER− mammary cancer cell lines, and found that E-cadherin expression increased and ZO-1 and Vimentin expression changed a little when compared with the overexpressed ER group." (PMID 31419991, 2019). "a-b There was no obvious change in the mRNA expression level of Lats1 when knocking down CRABP2 in ER+ and ER- mammary cancer cells." (PMID 31419991, 2019). "d-f The regulation of CRABP2 on the metastasis, and invasion depends on Lats1 in ER- mammary cancer cells." (PMID 31419991, 2019). "Meanwhile, CRABP2 promotes the degradation of Lats1 by promoting ubiquitination of Lats1 in ER− mammary cancer cells." (PMID 31419991, 2019). "RT-qPCR technique was used to examine the particular relation between CRABP2 and Lats1 in mammary cancer cells." (PMID 31419991, 2019). "Here we investigated the mRNA expression of Lats1 when knocking down CRABP2 in ER+ and ER− mammary cancer cells." (PMID 31419991, 2019). "In ER+ mammary cancer cells, the interaction of CRABP2 and Lats1 suppress the ubiquitination of Lats1 to activate Hippo pathway to inhibit the invasion and metastasis of ER+ mammary cancer." (PMID 31419991, 2019). "In ER− mammary cancer cells, the interaction of exogenous CRABP2 and Lats1 through an E3 ubiquitin ligase promotes the ubiquitination of Lats1 to promote the invasion and metastasis of ER− mammary cancer." (PMID 31419991, 2019). "The data presented in this study suggests that CRABP2 stabilize Lats1 by inhibiting ubiquitination of Lats1 in ER+ mammary cancer cells." (PMID 31419991, 2019). "CRABP2 serves as a positive regulator of RA signalling in breast cancer cells and its expression can be induced by RA in various cell types." (PMID 26142905, 2015). "Intriguingly, CRABP1 not only inversely regulates CRABP2 expression, but also affects nuclear translocation of CRABP2 in breast cancer cells." (PMID 26142905, 2015). "TFAP2A encodes AP-2α, recently shown to be essential for RA action, has previously been reported to stimulate CRABP2 expression in mammary epithelial cells and breast cancer cells." (PMID 26142905, 2015). "These combined data suggest the presence of a CRABP1-AP-2α-CRABP2 axis which modulates RA action in breast cancer cells." (PMID 26142905, 2015). "Again, these results suggest opposing roles for CRABP1 and CRABP2 in breast cancer clinical outcomes." (PMID 26142905, 2015). "Our results suggest that CRABP1, in addition to the previously identified FABP5 and CRABP2, is a key factor regulating breast cancer cell response to RA." (PMID 26142905, 2015). "The expression and subcellular distribution of two RA-binding proteins, FABP5 and CRABP2, has already been shown to play critical roles in breast cancer cell response to RA." (PMID 26142905, 2015). "In this study, we found that CRABP1 and CRABP2 have inverse expression patterns in breast tumors and play an opposing role in the mediation of RA action in breast cancer cells." (PMID 26142905, 2015). "To further understand the opposing roles of CRABP1 and CRABP2 in breast cancer progression, we immunostained our breast cancer TMA with Ki67, a cell proliferation marker, and examined its correlation with CRABP protein levels." (PMID 26142905, 2015). "Interestingly, CRABP2 has also been observed to exert inhibitory effects on breast cancer progression through distinct mechanisms." (PMID 39991584, 2025). "It has been reported that CRABP2 is expressed in lung cancer, breast cancer, and glioblastoma." (PMID 37004157, 2023).
breast carcinoma (continued). "Considering the controversial role of CRABP2 in different tumors, our previous pan-cancer analysis supported an association between high CRABP2 expression and adverse outcomes in breast, lung, and ovarian cancers, and the high level of CRABP2 promotes docetaxel resistance in breast cancer." (PMID 38186580, 2023). "However, the role of CRABP2 in breast cancer growth and metastasis has been interpreted differently." (PMID 36568517, 2022). "Previous findings indicated that CRABP2 promotes invasion and metastasis of ER− breast cancer." (PMID 36536459, 2022). "Furthermore, CRABP2 is highly expressed in pancreatic ductal adenocarcinoma, breast cancer, and non-small cell lung cancer (NSCLC), its high expression is associated with poor prognosis of patients with NSCLC or ER-negative breast cancer." (PMID 36568517, 2022). "In addition, CRABP2 regulates the metastasis and invasion of breast cancer through the Hippo pathway." (PMID 36195596, 2022). "In our study, CRABP2 is highly expressed in breast cancer, and lowly expressed in prostate cancer." (PMID 33407865, 2021). "The results indicate that CRABP2 is the significantly DEGs related to prostate and breast cancers." (PMID 33407865, 2021). "CRABP2 ′s role in breast cancer may be related to oestrogen signalling that suppresses the ubiquitination of Lats1 to activate the Hippo pathway, which inhibits invasion and metastasis in ER-positive tumours but not in ER-negative tumours." (PMID 32927694, 2020). "a-c Knockdown of CRABP2 promotes metastasis and invasion of ER+ breast cancer cells in vitro." (PMID 31419991, 2019). "Therefore, this study predominantly focuses on exploring the role of CRABP2 in different types of breast cancer in vitro and in vivo." (PMID 31419991, 2019). "This confirms that overexpression of ER in ER− breast cancer cells could reverse the inhibition of knocking down CRABP2 to breast cancer cells EMT." (PMID 31419991, 2019). "However, after knocking ER down in ER+ breast cancer, the reason for that CRABP2 overexpression still can stabilize Lats1 needs to be further explored." (PMID 31419991, 2019). "Likewise, knockdown of CRABP2 increased the expression of Lats1 when ER was overexpressed in ER− breast cancer cells." (PMID 31419991, 2019). "We guessed what the mechanism might be that ER is more capable of binding to E3 ubiquitin ligase of Lats1 than CRABP2 in ER+ breast cancer cells." (PMID 31419991, 2019). "CRABP2 prevents the growth of breast cancer cells by two different mechanisms." (PMID 31419991, 2019). "Our study showed that the protein expression of CRABP2 in breast cancer is related to ER." (PMID 31419991, 2019). "However, the protein expression of p-Lats1T1079, Lats1, p-YAPS127 in the Hippo pathway were reduced, maintaining the expression levels of YAP and Mst2 when knocking down CRABP2 in ER+ breast cancer cells." (PMID 31419991, 2019). "So we hypothesized whether the biological function of CRABP2 in regulating breast cancer was related to CRABP1." (PMID 31419991, 2019). "On the other hand, there is evidence that favor and opposes the role of CRABP2 in breast cancer." (PMID 31419991, 2019). "This suggested that CRABP2 plays different roles depending on the type of breast cancer." (PMID 31419991, 2019). "Also, CRABP2 cannot bind to E3 ubiquitin ligase to suppress ubiquitination of Lats1 to repress invasion and metastasis of ER+ breast cancer." (PMID 31419991, 2019). "Above all, we found that CRABP2 was more highly expressed in ER+ than in ER− breast cancer tissues." (PMID 31419991, 2019). "Thus, from these results, we conclude that that CRABP2 mediates ubiquitination of Lats1 in mammary cancer cells relying on ER status." (PMID 31419991, 2019). "Moreover, silencing and overexpressing CRABP2 in ER+ and ER− mammary cancer cells induces EMT and promotes mammary cancer cells invasion and metastasis." (PMID 31419991, 2019).